TYMP (thymidine phosphorylase)
Diseases named in the same sentence as TYMP in open-access papers (continued):
Sharing a sentence is not in itself a finding about the gene and the disease.
Granuloma (1 paper, 2024). A compact, organized collection of mature mononuclear phagocytes, which may be but is not necessarily accompanied by accessory features such as necrosis. "Similar to TYMP and LAP3, the upregulated expression of ANXA3 in the blood samples may be closely related to angiogenesis in the granulomas of patients with PTB." (PMID 39023413, 2024).
inflammatory bowel disease (1 paper, 2023). A spectrum of small and large bowel inflammatory diseases of unknown etiology. "Our study showed that 2’-deoxyuridine was lower in inflammatory bowel disease (IBD) through TYMP locus (rs140522, p = 3.98 × 10−57) by MWAS, and consistently, a recent study showed that high uridine/2’-deoxyuridine ratio was causal for IBD2." (PMID 37333177, 2023).
insulin-resistant diabetes (1 paper, 2022). "All patients had TYMP loss-of-function variants and first presented with generalized loss of adipose tissue and insulin-resistant diabetes." (PMID 35341481, 2022).
intestinal gastric adenocarcinomas (1 paper, 2021). "TYMP is commonly reported to play a major role in 5-FU chemoresistance and is often found to be overexpressed in both diffuse and intestinal gastric adenocarcinomas." (PMID 34299320, 2021).
kidney cancer (1 paper, 2023). Primary or metastatic malignant neoplasm involving the kidney. "Scholars have identified kidney cancer biomarkers, such as nicotinamide N-methyl transferase, serum amyloid protein, thymidine phosphorylase, and other biomarkers that can be used to diagnose renal cancer 13-16." (PMID 37056387, 2023).
kidney tumors (1 paper, 2008). "In comparison with normal kidney tissue, thymidine phosphorylase was found in higher concentrations in kidney tumors, at a ratio of almost 7:1." (PMID 18794792, 2008).
leiomyoma (1 paper, 2014). A well-circumscribed benign smooth muscle neoplasm characterized by the presence of spindle cells with cigar-shaped nuclei, interlacing fascicles, and a whorled pattern. "Compared to leiomyomas, only a few pro-angiogenic factors such as TYMP, ANGPTL2 and PTGS1 were increased in PTSMT." (PMID 24398114, 2014).
leukemia (1 paper, 2020). A malignant (clonal) hematologic disorder, involving hematopoietic stem cells and characterized by the presence of primitive or atypical myeloid or lymphoid cells in the bone marrow and the blood. "Therefore, we performed additional in vitro experiments based on the two best 5-protein models (which shared TYMP, RRM1, UPP1, and UCK1 and contained either PPAT or UCK2) using two CRC and two leukemia cell lines that are predicted to be sensitive or resistant to 5FU." (PMID 32686665, 2020).
lipoatrophic diabetes (1 paper, 2022). A rare syndrome characterized by almost complete absence of body fat, accentuated muscularity, insulin-resistant diabetes, hyperlipidemia, hepatomegaly, and hypermetabolism. "Deep phenotyping was performed in three patients from two families carrying homozygous TYMP variants and presenting with lipoatrophic diabetes." (PMID 35341481, 2022). "This translational study identifies biallelic TYMP pathogenic variants as a new genetic cause of monogenic lipoatrophic diabetes due to mitochondrial dysfunction." (PMID 35341481, 2022). "This study shows that TYMP analysis should enter genetic routine diagnosis of monogenic lipoatrophic diabetes." (PMID 35341481, 2022).
liver cancer (1 paper, 2015). An epithelial or non-epithelial malignant neoplasm that arises from the liver. "In vivo validation of the combined treatment of TYMP shRNA suppression plus dT-QX was carried out in a subcutaneous tumor model of human liver cancer Bel-7402 cells." (PMID 25881156, 2015). "In contrast, levels of TYMP protein varied dramatically among liver cancer cells but remained at a low level in normal liver cells." (PMID 25881156, 2015). "The counteraction of TYMP was further supported by the difference in cytotoxicity observed between Hep3B and other liver cancer cells that had high levels of TYMP." (PMID 25881156, 2015). "In this study, we reported the involvement of TK1 and TYMP in the biological activity of thymidine analog dT-QX in different liver cancer cell lines, methods to enhance the anticancer selectivity and in vivo study with a mouse tumor model." (PMID 25881156, 2015). "Therefore, the results from our siRNA suppression and viral overexpression studies indicated that high levels of cytosolic TK1 were responsible for the cytotoxicity of dT-QX in liver cancer cells while high levels of TYMP counteracted the biological activity." (PMID 25881156, 2015). "Thus, high levels of TYMP in liver tumors are important subtypes and/or variations of liver cancers that need to be addressed specifically due to TYMP as a growth factor in tumors." (PMID 25881156, 2015). "By taking advantage of low levels of TK1 and TYMP in normal liver tissue, the use of anticancer thymidine conjugate combined with TYMP suppression could directly target thymidine salvage pathway in liver cancer cells with various levels of TYMP addressed as tumor heterogeneity to be fully inhibited." (PMID 25881156, 2015). "We found that the thymidine conjugate had varied activities in liver cancer cells with different levels of TK1 and TYMP." (PMID 25881156, 2015).
liver cirrhosis (1 paper, 2022). "When compared to healthy controls, only 7 DEGs, including 6 up-DEGs (TYMP, TYROBP, TGFBI, LILRA2, GNLY, and GZMB) and 1 down-DEG (CD14) were common to CHB, liver cirrhosis, and HCC." (PMID 35265561, 2022).
liver fibrosis (1 paper, 2024). "Increased thymidine phosphorylase (TYMP) in siCD36 macrophages is related to metabolic processes promoting liver fibrosis." (PMID 39083563, 2024).
Lyme disease (1 paper, 2020). Lyme disease (named after the towns in the USA where the disease was first identified) is a bacterial infection caused by Borrelia burgdorferi. "Previous studies identified peptides from annexin A2, apolipoprotein B-100, thymidine phosphorylase (endothelial cell growth factor), and stromelysin-2 (matrix metalloproteinase 10) as targets of autoreactive T cells in a subset of human Lyme disease patients." (PMID 33043033, 2020).
Mitochondrial myopathy (1 paper, 2020). "We applied a next-generation sequencing panel to increase the diagnostic rate in a group of adult patients featuring muscle mtDNA deletions, and we disclosed TYMP variants in three subjects, two of them manifesting mainly isolated mitochondrial myopathy." (PMID 32849836, 2020).
mucoepidermoid carcinoma of the lung (1 paper, 2014). "We have demonstrated the regulation of thymidine phosphorylase by Nrf2 and HO-1 in mucoepidermoid carcinoma of the lung, as the manipulation of Nrf2 or HO-1 levels led to concomitant modulation of TP levels in vitro and in vivo and HO-1 expression correlated with TP in clinical NSCLC specimens." (PMID 24819505, 2014).
mycosis fungoides (1 paper, 2011). Classical mycosis fungoides is the most common type of mycosis fungoides (MF), a form of cutaneous T-cell lymphoma, and is characterized by slow progression from patches to more infiltrated plaques and eventually to tumors. "We demonstrated that thymidine phosphorylase staining is present in neoplastic T cells in mycosis fungoides." (PMID 22162690, 2011). "Our study explores thymidine phosphorylase expression in lymph nodes (LNs) from patients with mycosis fungoides (MF) or Sézary syndrome (SS)." (PMID 22162690, 2011).
non-alcoholic fatty liver disease (1 paper, 2025). "TYMP, linked to apoptosis and inflammation, is downregulated in non-alcoholic fatty liver disease(NAFLD) and modulates the NF-κB pathway in acute liver injury models, suggesting a protective role in PBC." (PMID 41142241, 2025).
optic atrophies (1 paper, 2023). "Moreover, variants in nuclear genes OPA1, OPA3, TYMP and POLG have been reported in patients with other optic atrophies with phenotypes that could be similar to LHON." (PMID 36827238, 2023).
pancreatic adenocarcinoma (1 paper, 2023). "Furthermore, the combination of Capecitabine (a prodrug that is converted to 5-FU by thymidine phosphorylase) and Celecoxib (a Cox-2 inhibitor) reduced the number of mice with pancreatic adenocarcinoma, which was associated with a recovery of SOD and CAT activity." (PMID 36776312, 2023).
prostate tumours (1 paper, 2002). "Thymidine phosphorylase may be a target for cytotoxic and anti-angiogenic therapeutic strategies in prostate tumours." (PMID 11986782, 2002).
psoriasis vulgaris (1 paper, 2024). Plaque psoriasis is the most common presentation of psoriasis. "Previous research had found TYMP participated in drug metabolism-other enzyme pathways and played crucial roles in activating and proliferating immune cells in psoriasis vulgaris." (PMID 39480805, 2024).
rheumatoid arthritis (1 paper, 2022). A chronic, systemic autoimmune disorder characterized by inflammation in the synovial membranes and articular surfaces. "TYMP also enhanced C-X-C motif chemokine 10 (CXCL10) production in an in vitro model of rheumatoid arthritis, while this chemokine is also described as a urinary biomarker of ABMR." (PMID 35327371, 2022).
schizophrenia (1 paper, 2024). A major psychotic disorder characterized by abnormalities in the perception or expression of reality. "However, mitochondrial neurogastrointestinal dysfunction, associated with biallelic variants in the TYMP gene, was observed commonly in schizophrenia." (PMID 38573526, 2024).
steatosis (1 paper, 2023). Increased lipid within the cytoplasm of cells. "The logistic regression model, -34.19 + 0.85 * QDPR*QDPR + 0.75 * CANT1*TYMP - 0.46 * THOP1*ALDH1A, achieved an AUC of 0.93 (95% CI: 0.63-0.99), with a sensitivity of 93% and specificity of 80% for detecting steatosis in individuals with PWS." (PMID 38034016, 2023).
thyroid cancer (1 paper, 2025). "Collectively, these findings suggest that M2‐like myeloid cells, particularly TYMP+ TAMs, undergo spatial and functional reprogramming during dedifferentiation and may serve as critical mediators of the aggressive phenotype in thyroid cancer." (PMID 40908584, 2025).
transitional cell carcinoma (1 paper, 2005). A malignant neoplasm arising from the transitional epithelium, usually affecting the urinary bladder, ureter, or renal pelvis. "We also demonstrate that thymidine phosphorylase overexpression confers tumorigenicity on an orthotopically implanted transitional cell carcinoma cell line." (PMID 15841086, 2005).
transitional cell carcinoma of the bladder (1 paper, 2005). "Elevated thymidine phosphorylase has been shown to correlate with increased angiogenesis and poor prognosis in many cancers including transitional cell carcinoma of the bladder." (PMID 15841086, 2005).
tuberculosis (1 paper, 2024). A chronic, recurrent infection caused by the bacterium Mycobacterium tuberculosis. "For example, a panel of markers, such as TYMP, LAP3, ANXA, and SULF1, along with traditional tuberculosis‐related symptoms such as persistent cough, weight loss, and fever, can be used to differentiate between patients with cancer, post‐SARS‐CoV‐2 infection, and those at risk for tuberculosis." (PMID 39023413, 2024). "The results of ROC showed that TYMP (AUC = 0.964), LAP3 (AUC = 0.914), ADGRL2 (AUC = 0.98), SIL1 (AUC = 0.936), LMO7 (AUC = 0.856), SULF1 (AUC = 0.96), ANXA3 (AUC = 0.798), and PACSIN3 (AUC = 0.747) had high accuracy in predicting tuberculosis." (PMID 39023413, 2024).
uterine cancer (1 paper, 2008). Primary or metastatic malignant neoplasm involving the uterine corpus and/or the cervix. "The angiogenic factors vascular endothelial growth factor (VEGF) and thymidine phosphorylase identified with platelet-derived endothelial cell growth factor and interleukin (IL-8) along with the angiogenic transcriptional factor ETS-1 work on angiogenesis in uterine cancers." (PMID 19002177, 2008).
viral infections (1 paper, 2021). "By searching GEO (Gene Expression Omnibus) profile using keywords “TYMP + virus,” we found that TYMP was also upregulated in several other viral infections, including influenza virus H1N1 infected bronchia epithelial cells and Sendai-virus infected monocytes." (PMID 33829029, 2021).
vitiligo (1 paper, 2025). Generalized well circumscribed patches of leukoderma that are generally distributed over symmetric body locations and is due to autoimmune destruction of melanocytes. "This analysis identified four genes—STAT1, VAMP5, LAP3, and TYMP—that exhibited both strong module membership and significant upregulation in vitiligo." (PMID 41498037, 2025).
tumor (151 papers, 1997 to 2026). "SP markedly increased lung tumor incidence and aggressiveness, whereas TYMP deficiency reduced tumor formation from 50% to 18% of lung lobes." (PMID 41988188, 2026). "For example, high HIF-2α protein expression in tumor-associated macrophages has been correlated with increased tumor microvessel density, decreased thymidine phosphorylase, and advanced tumor grade in human breast cancer." (PMID 37124241, 2023). "In tumor epithelial cells, high TYMP gene expression was associated with shorter RFS, independent of known risk factors." (PMID 35567733, 2022). "TYMP expression in tumor epithelial cells was associated with RFS and emphasizes the need for tissue microdissection." (PMID 35567733, 2022). "Thymidine phosphorylase in tumour cells tended to be co-upregulated with TP in tumour-associated stromal cells such as macrophages, indicating a possible role for microenvironmental factors in this response." (PMID 15150550, 2004). "Thymidine phosphorylase is an angiogenic factor primarily expressed by cancer cells, stromal cells and tumour-associated macrophages in many human malignancies." (PMID 11986782, 2002). "Additionally, TYMP expression in CRC tumor epithelial cells is linked to recurrence-free survival (RFS) in patients with CRC." (PMID 40303404, 2025). "The down-regulation of pathways in cancer is noteworthy, particularly given that thymidine phosphorylase is upregulated across a broad spectrum of solid tumours, where its elevated expression is associated with increased tumour growth, metastasis, angiogenesis, and poor prognosis." (PMID 41009664, 2025). "Notably, TYMP+ tumor‐associated macrophages (TAMs) were highly enriched in ATC regions and contribute to an immunosuppressive microenvironment." (PMID 40908584, 2025). "Notably, PDCD4 loss drives eIF4A‐dependent upregulation of immunosuppressive effectors, promoting TYMP+ tumor‐associated macrophages enrichment, which represents a key mechanism in establishing the immunosuppressive microenvironment of ATC." (PMID 40908584, 2025). "In addition, high levels of TYMP in tumor endothelium are linked to increased angiogenesis and a poor prognosis." (PMID 37100811, 2023). "Reports of downregulation of IRF1 in endometrial tumorigenesis are common; however, derepression of IRF1 may occur in a subset of tumors, an event which is associated with thymidine phosphorylase upregulation and aggressive tumor behavior." (PMID 35993041, 2022). "Capecitabine undergoes enzymatic conversion to 5-FU, with the final activation step occurring predominantly in tumor tissues owing to high thymidine phosphorylase expression." (PMID 40920146, 2025). "Beyond its role in normal cells, TYMP is also pivotal in cancer cells, where it facilitates tumor angiogenesis, modifies epigenetics, and helps resist cell apoptosis." (PMID 40303404, 2025). "This article provides a comprehensive review of TYMP’s structure, physiological functions, and its role in tumorigenesis and anti-tumor therapy." (PMID 40303404, 2025). "Studies have shown that the expression levels of thymidylate synthase (TYMS) and TYMP in tumor tissues are significantly higher than in adjacent normal tissues." (PMID 40303404, 2025). "Given that tumor growth depends on cell division, TYMP’s involvement in cell proliferation and tumor development suggests its critical role in cancer progression." (PMID 40303404, 2025). "In contrast, thymidine phosphorylase (TP) gene therapy aims to enhance the sensitivity of tumor cells to prodrugs such as 5-fluorouracil (5-FU) and 5′-deoxy-5-fluorouridine (5′-DFUR) by transfecting cancer cells with TP." (PMID 40510154, 2025). "Capecitabine undergoes a 3-step conversion process to 5-FU, with the final step being catalysed by thymidine phosphorylase – an enzyme with higher activity in many types of tumour tissues." (PMID 40600575, 2025).